TIMP2 (TIMP metallopeptidase inhibitor 2)
Diseases named in the same sentence as TIMP2 in open-access papers (continued):
Sharing a sentence is not in itself a finding about the gene and the disease.
acute kidney injury (70 papers, 2014 to 2025). Sudden and sustained deterioration of the kidney function characterized by decreased glomerular filtration rate, increased serum creatinine or oliguria. "We found that heat stress increased plasma creatinine and cystatin C, in addition to urinary IGFBP7 × TIMP‐2, collectively indicating a potential risk for acute kidney injury." (PMID 39417775, 2025). "Changes in the concentration of [TIMP-2] [IGFBP7] in urine after fluid resuscitation could be used to differentiate the risk of developing sepsis for patients with acute kidney injury." (PMID 38259686, 2023). "In this regard, recent trials have shown that, in a selection of patients undergoing cardiac surgery, using blood biomarkers associated with high risk for acute kidney injury (AKI) (like TIMP-2) reduced the rate and severity of AKI." (PMID 39003476, 2024). "The first FDA-approved test to assess risk for acute kidney injury (AKI), [TIMP-2]•[IGFBP7], is clinically available in many parts of the world, including the USA and Europe." (PMID 31221200, 2019). "Neutrophil gelatinase‐associated lipocalin (NGAL) and tissue inhibitor of metalloproteinase‐2 (TIMP‐2) have potential as early biomarkers for acute kidney injury (AKI) in dogs." (PMID 40008829, 2025). "Elevated urinary IGFBP-7 and TIMP-2 levels reflect acute kidney injury (AKI), renal tubular damage, and fibrosis common in MM due to plasma cell infiltration and light chain deposition." (PMID 40369504, 2025). "•The authors analysed the impact of propofol or sevoflurane anaesthesia on RIPC in reducing acute kidney injury (AKI) after cardiac surgery as reflected in the cell cycle arrest biomarkers TIMP-2 and IGFBP7 in urine." (PMID 41093687, 2025). "In conclusion, TIMP-2 × IGFBP-7 is considered a more reliable indicator for predicting or diagnosing poor prognosis or even mortality in patients with acute renal failure following cardiac surgery." (PMID 38788006, 2024). "The authors found that urinary TIMP2 × IGFBP-2 is an early predictor of acute kidney injury and increased precociously in acute septic kidney injury after cardiac surgery." (PMID 38137505, 2023). "Previous studies have shown that TIMP2 levels increased in acute kidney injury, and downregulation of TIMP2 ameliorated renal injury by inhibiting the NF-κB pathway by exerting anti-inflammatory activity." (PMID 36578555, 2022). "It is noteworthy that TIMP2 IGFBP7 has been approved by the US Food and Drug Administration as an aid in the risk assessment for moderate or severe (stage 2–3) acute kidney injury within the next 12 h." (PMID 34641779, 2021). "The urinary tissue inhibitor of metalloproteinases-2 and insulin-like growth factor-binding protein 7 ([TIMP-2]∙[IGFBP7]) have been introduced to improve risk prediction of severe acute kidney injury (AKI) within 12 hours of measurement." (PMID 31712687, 2019). "Monitoring urine biomarkers, such as tissue inhibitor of metalloproteinases-2 (TIMP-2) and insulin-like growth factor-binding protein 7 (IGFBP-7), for acute kidney injury in high-risk patients may help guide interventions." (PMID 40843750, 2025). "In a prospective cohort trial of 557 adult patients undergoing cardiac surgery, urinary TIMP-2 combined with IGFBP-7 was an excellent early indication of cardiac surgery-associated acute kidney injury (CSA-AKI) and related short-term negative outcomes." (PMID 39001241, 2024). "In sepsis-associated acute kidney injury (SA-AKI), TIMP-2 enhances ER stress-induced apoptosis." (PMID 39001241, 2024). "The Nephrocheck® test is a single-use cartridge designed to measure the concentrations of two novel cell-cycle arrest biomarkers of acute kidney injury, namely tissue inhibitor of metalloproteinase 2 (TIMP-2) and insulin-like growth factor binding protein 7 (IGFBP7)." (PMID 35252280, 2022).
acute kidney injury (continued). "It has been demonstrated that TIMP-2 and IGFBP7 are useful in predicting acute kidney injury following cardiac surgery, and compared with other biomarkers, TIMP-2 and IGFBP7 might be useful to predict the onset of severe AKI." (PMID 36313991, 2022). "The aim of this study was to evaluate uCHI3L1 as a biomarker for AKI in ICU patients included in the multicenter Finnish Acute Kidney Injury (FINNAKI) study and compare this to the NephroCheck Risk® score, the composite of the cell cycle arrest biomarkers TIMP-2 and IGFBP7." (PMID 32276601, 2020). "Diagnostic value of urinary TIMP-2 and IGFBP7 for acute kidney injury in individual studies." (PMID 31261582, 2019). "Furthermore, TIMP-1 has been confirmed to be a predictor of clinical outcomes in patients with severe sepsis, while TIMP-2 is regarded as an early biomarker for predicting acute kidney injury (AKI), which is a common complication of sepsis." (PMID 31671729, 2019). "Most previous studies have focused on IGFBP7 and TIMP-2 for their role in acute kidney injury (AKI) prediction." (PMID 35327386, 2022). "While it did not impact cardiac parameters, empagliflozin significantly reduced markers of acute kidney injury (AKI), specifically TIMP-2 and IGFBP7, indicating protection against tubular kidney damage." (PMID 38255264, 2024). "The urinary biomarker combination [TIMP-2] × [IGFBP7], which are both markers for G1 cell cycle arrest, has been identified and validated to predict moderate to severe acute kidney injury in critically ill patients earlier than other known biomarkers." (PMID 38673754, 2024). "The cell cycle arrest biomarkers tissue inhibitor of metalloproteinase‐2 (TIMP‐2) and insulin like growth factor binding protein 7 (IGFBP7) have shown to be valuable biomarkers for early detection of acute kidney injury (AKI) in people." (PMID 38053473, 2023). "Kashani K’s study demonstrated that NAGL was weaker than NephroCheck and urinary TIMP-2/IGFBP7, but stronger than plasma cystatin C and urine KIM-1 in predicting acute kidney injury." (PMID 35887790, 2022). "It is worth noting that two markers which have attracted a lot of interest in the prediction of acute kidney injury, IGFBP-7 and TIMP-2, seem to be differently affected by TCEP reduction." (PMID 32111925, 2020). "Tissue inhibitor of metalloproteinase-2 (TIMP-2) and insulin-like growth factor binding protein 7 (IGFBP7) are recently identified urinary biomarkers of acute kidney injury (AKI) in critically ill patients." (PMID 31261582, 2019). "In various models of acute kidney injury (AKI), which are mostly produced by renal ischemia-reperfusion injury, not only increased expressions of MMP-2, -9 and TIMP-2, but also decreased expression of TIMP-1 have been observed." (PMID 27455234, 2016). "The recent discovery of cell cycle arrest biomarkers, tissue inhibitor of metalloproteinases (TIMP)-2 and insulin-like growth factor binding protein 7 (IGFBP7), has led to a newly available clinical test for acute kidney injury." (PMID 27245788, 2016). "In this experimental model of sepsis in the rat, cell cycle arrest biomarkers TIMP-2 and IGFBP7 are valid predictors of acute kidney injury." (PMID 27245788, 2016). "We measured TIMP-2 and IGFBP7 and compared the results to acute kidney injury by RIFLE criteria for creatinine using area under the receiver operating characteristic curve (AUC)." (PMID 27245788, 2016). "The cell cycle arrest biomarkers tissue inhibitor of metalloproteinases-2 (TIMP-2) and insulin-like growth factor-binding protein 7 (IGFBP7) have emerged as promising indicators for detecting acute kidney injury (AKI), particularly in critically ill patients and those undergoing cardiac surgery." (PMID 40807208, 2025). "It therefore seems very reasonable that cut-off values of urinary [TIMP-2] × [IGFBP7] for non-DGF are higher than those validated for the identification of acute kidney injury in critically ill adults." (PMID 38673754, 2024).
acute kidney injury (continued). "For the detection of cardiac surgery-associated acute kidney injury (CS-AKI), the performance of urine tissue inhibitor of metalloproteinase 2 insulin-like growth factor-binding protein 7 (TIMP2 IGFBP7) has never been compared with that of very early changes in plasma creatinine (∆pCr)." (PMID 34641779, 2021). "Insulin-like growth factor binding protein 7 (IGFBP-7) and tissue inhibitor of metalloproteinases 2 (TIMP-2), which are secreted soluble proteins as part of the uEV proteome, are of great interest as biomarkers to predict the risk of developing acute kidney injury (AKI)." (PMID 32111925, 2020). "The urinary biomarkers TIMP-2 and IGFBP7, which are released in stressed cells as an “alarm signal” for adjacent cells, have recently been established as early predictors of imminent acute kidney injury (AKI) in general and postoperative patients." (PMID 29973233, 2018). "Such physiological and pathological mechanisms lead to increased urinary TIMP2 and IGFBP7 levels in acute kidney injury and their role in the early prediction of AKI." (PMID 37055509, 2023). "Can measuring the cell-cycle arrest biomarkers tissue inhibitor of metalloproteinases 2 (TIMP-2) and insulinlike growth factor binding protein 7 (IGFBP7) enhance acute kidney injury (AKI) staging using a recently proposed framework?" (PMID 35583867, 2022). "Valuable biomarkers indicative of acute kidney injury (AKI) are insulin-like growth factor-binding protein 7 (IGFBP7), tissue inhibitor of metalloproteinases-2 (TIMP-2); their levels in urine need to be monitored on urgent basis." (PMID 31750312, 2019). "The product of the concentrations of urinary tissue inhibitor of metalloproteinases-2 and insulin-like growth factor binding protein-7 (urinary [TIMP-2] × [IGFBP-7]) has been suggested as biomarker for early detection of acute kidney injury (AKI) in various clinical settings." (PMID 31315590, 2019). "The capability of urinary TIMP-2 (tissue inhibitor of metalloproteinase) and IGFBP7 (insulin-like growth factor binding protein)—NephroCheck Test (NC) = ([TIMP-2] x [IGFBP7]) / 1000)—to predict renal recovery from acute kidney injury (AKI) has been poorly studied." (PMID 28085896, 2017). "In recent months it has proved to be clear that a single biomarker would not suffice for the diagnosis of acute kidney injury, instead, it has been elaborated that a consortium of peptides such as KIM-1, NGAL, IL18 and IGFB7, TIMP-2 will be indicative for injuries of the nephron." (PMID 28545475, 2017).
Sepsis (54 papers, 2013 to 2025). Sepsis is defined as life-threatening organ dysfunction caused by a dysregulated host response to infection. "TIMP2 protects against sepsis-associated acute kidney injury by cAMP/NLRP3 axis-mediated pyroptosis." (PMID 40989844, 2025). "In this study, we aimed to evaluate the diagnostic value of several MMPs (MMP-2, MMP-9, MMP-8) and TIMPs (TIMP-1 and TIMP-2) for equine colic, which is often associated with endotoxemia and sepsis in case of strangulating obstruction." (PMID 33488296, 2021). "The fact that [TIMP-2]·[IGFBP7] are independently associated with AKI in sepsis is a relevant advantage of these biomarkers compared with more widely described NGAL or cystatin-C." (PMID 28884304, 2017). "In conclusion, we have validated the [TIMP-2]·[IGFBP7] test in an experimental model of sepsis-associated AKI using CLP." (PMID 27245788, 2016). "Whereas neither TIMP-2 nor IGFBP7 was elevated in patients without AKI being unaffected by important co-morbidities such as chronic kidney disease, diabetes, and sepsis, patients with a [TIMP-2]*[IGFBP7] greater than 0.3 had seven times the risk for AKI." (PMID 26669781, 2015). "Another multicenter study conducted in ED included approximately half of the patients with sepsis; urinary TIMP-2 × IGFBP-7 improved the predictive power for both AKI and 30-day mortality." (PMID 39811377, 2025). "A recent study showed that TIMP2*IGFBP7 is also an accurate predictor of the need for RRT in sepsis-induced AKI." (PMID 39596140, 2024). "This study compared a three-level kidney-sparing sepsis bundle based on the KDIGO recommendations and guided by risk stratification using serial measurement of urinary [TIMP-2] x [IGFBP7] in patients with sepsis." (PMID 39279017, 2024). "The group of rats with sepsis showed higher expression of TIMP-2 and pyroptosis-related proteins (NLRP3, IL-1β, caspase-1, and GSDMD) compared to the sham-operated group, suggesting pyroptosis plays a role in AKI." (PMID 39001241, 2024). "In sepsis-associated AKI (SA-AKI), TIMP-2 levels combined with clinical prognostic models improved predictive accuracy (AUC: 0.822)." (PMID 39001241, 2024). "Immunohistochemical examination of the kidneys revealed that TIMP-2 was continuously expressed in the sepsis-induced group throughout the trial." (PMID 39001241, 2024). "TIMP-2 and IGFBP7 are produced and released by renal tubular cells in the early stages of injury caused by various injuries (such as sepsis, ischemia, and oxidative stress)." (PMID 37671089, 2023). "IGFBP7 and TIMP-2 are proteins expressed in renal tubular cells during periods of cellular stress or injury, particularly in sepsis." (PMID 36545669, 2022). "U[TIMP-2]*[IGFBP7], uKIM-1 and uIL-18 predicted the progression of AKI in sepsis, with u[TIMP-2]*[IGFBP7] presented the greatest AUC (0.745, 95%CI 0.667-0.823) as compared to uKIM-1 (AUC 0.719, 95%CI 0.638-0.800) and uIL-18 (AUC 0.619, 95%CI 0.525-0.713)." (PMID 34906098, 2021). "In this prospective study in patients with sepsis, we further directly compared the predictive performance of u[TIMP-2]*[IGFBP7] with the other novel injury/inflammation biomarkers in single or combination." (PMID 34906098, 2021). "Compared to the FDA approved AKI biomarker [TIMP2]*[IGFBP7], miR-452, especially urinary miR-452, showed high diagnostic efficiency for AKI in sepsis patients." (PMID 33204323, 2020). "The sensitivity of urinary miR-452 for AKI detection in sepsis patients reached 87.23%, which was remarkably higher than the sensitivity of [TIMP2]*[IGFBP7] (61.54%) examined in the same cohort of sepsis patients." (PMID 33204323, 2020). "Like procalcitonin in sepsis, the role of [TIMP-2]∙[IGFBP7] is to guide the clinician in a timely manner for further intervention of the patients at risk." (PMID 31712687, 2019). "In a CLP model of sepsis, the combination of TIMP-2 and IGFBP-7 has greater sensitivity in diagnosis of AKI compared with serum creatinine." (PMID 28430696, 2017).
Sepsis (continued). "Actually, TIMP-2 has been identified as a potential new AKI biomarker by examination of over 300 markers with a heterogeneous AKI cohort comprising sepsis, shock, major surgery and trauma." (PMID 25524453, 2014). "However, when combined with plasma creatinine, TIMP-2 × IGFBP-7 showed potential to improve AKI prediction in sepsis patients presenting to the emergency department, as indicated by a significant result in the DeLong's test." (PMID 39811377, 2025). "Additionally, sepsis and other disorders can increase TIMP-2 levels, and this can undermine its ability to accurately detect kidney injury." (PMID 39001241, 2024). "Furthermore, IGFBP-7 and TIMP-2 are closely associated with AKI induced by factors, such as cardiac surgery, kidney transplantation, decompensated heart failure, cardiac arrest, sepsis, and toxic nephropathy." (PMID 38788006, 2024). "This difference might be explained by assuming that urinary IGFBP7 was superior to urinary TIMP-2 in surgical patients, while urinary TIMP-2 was best in sepsis-induced AKI." (PMID 35197070, 2022). "u[TIMP-2]*[IGFBP7], measured at time of septic AKI diagnosis, could not only be used as a tool assessing the risk of AKI progression in sepsis, but also provided additional prognostic information in hospital, such as subsequent death after AKI." (PMID 34906098, 2021). "Previous studies reported that urine [TIMP-2]*[IGFBP7] could be used for early diagnosis and risk prediction in sepsis-associated AKI." (PMID 32487237, 2020). "The product of the urinary concentrations of tissue inhibitor of metalloproteinases-2 (TIMP-2) and insulin-like growth factor-binding protein 7 (IGFBP7) has been validated for use in the early identification of sepsis-associated AKI and for risk stratification in this context." (PMID 32487237, 2020). "We further evaluated the urinary [TIMP2]*[IGFBP7] in the sepsis patient cohort." (PMID 33204323, 2020). "Variability in the timing of urine sampling may have affected urine [TIMP-2]*[IGFBP7] values, particularly as the time from kidney injury cannot be clearly determined in patients presenting with sepsis-associated AKI." (PMID 32487237, 2020). "MMP-9, TIMP-2 and TIMP-1 have been shown to be elevated in patients with severe sepsis and septic shock as well as in animal models of endotoxemia, while MMP-1, MMP-8 and MMP-13 have also been associated with sepsis." (PMID 30466423, 2018). "We observed better performance for TIMP-2 in this experimental model of sepsis." (PMID 27245788, 2016). "Sepsis appeared to have a limited impact on urinary TIMP-2, in contrast to plasma NGAL." (PMID 25524453, 2014). "Continuous NRI and IDI revealed that the biomarkers that are less influenced by sepsis—TIMP-2, NAG and EPO—improved prediction of severe AKI in the septic population when added to the clinical model, which incorporated age, sex, complication of diabetes, medical admission and serum creatinine." (PMID 25524453, 2014). "Sepsis appeared to have only a limited impact on urinary TIMP-2, in contrast to plasma NGAL." (PMID 25524453, 2014). "Also of interest is that IGFBP7 is superior to TIMP-2 in surgical patients while TIMP-2 is best in sepsis-induced AKI." (PMID 23388612, 2013). "Indeed, different performances of each component, such as observed in other settings, with TIMP-2 outperforming IGFBP-7 for sepsis-induced AKI diagnosis and IGFBP-7 being superior in the surgical setting, could not be evaluated." (PMID 30400873, 2018). "Thus, we sought to evaluate the performance of [TIMP-2]·[IGFBP7] in an rat model of sepsis." (PMID 27245788, 2016). "[TIMP-2]• [IGFBP7] exhibited predictive value for AKI with an AUC of 0.86 (95% CI 0.75-0.90) in stroke, 0.82 (95% CI 0.74-0.91) in sepsis, and 0.90 (95% CI 0.82-0.98) in post-cardiac surgery." (PMID 41071816, 2025).